Y_RNA (Y RNA )
Gene: Miscellaneous RNA gene on chromosome 1 (247,294,835 to 247,294,941, forward strand). Ensembl gene ENSG00000202079.
Homologues: Orthologues: chimpanzee Y_RNA (100% identical), macaque Y_RNA (94% identical). Paralogues in human: RNY1 (82% identical), Y_RNA (82% identical), Y_RNA (81% identical), Y_RNA (80% identical), Y_RNA (79% identical), RNY1P11 (79% identical), RNY1P15 (79% identical), RNY1P10 (78% identical), Y_RNA (78% identical), RNY1P13 (77% identical), Y_RNA (77% identical), RNY1P8 (76% identical), and 93 more.